ATP6V0E1 (ATPase H+ transporting V0 subunit e1)
Description:
Subunit of the V0 complex of vacuolar(H+)-ATPase (V-ATPase), a multisubunit enzyme composed of a peripheral complex (V1) that hydrolyzes ATP and a membrane integral complex (V0) that translocates protons. V-ATPase is responsible for acidifying and maintaining the pH of intracellular compartments and in some cell types, is targeted to the plasma membrane, where it promotes acidification of the extracellular environment (By similarity). The V-ATPase complex also acts as an activator for mTORC1 on lysosomal membrane by promoting the guanine nucleotide exchange factor (GEF) of the Ragulator complex, thereby enabling mTORC1 recruitment.
Synonyms: ATP6H; ATP6V0E; M9.2; Vma21; Vma21p
Tractability: Small molecule: a structure with a bound ligand is known. Antibody: UniProt predicts a signal peptide or a membrane-spanning region.
Gene: Protein-coding gene on chromosome 5 (172,983,771 to 173,035,445, forward strand). Ensembl gene ENSG00000113732.
Subcellular location: Membrane
Pathways (Reactome):
Transport of small molecules: Ion channel transport; Transferrin endocytosis and recycling
Cellular responses to stimuli: Amino acids regulate mTORC1
Developmental Biology: Regulation of MITF-M-dependent genes involved in lysosome biogenesis and autophagy
Immune System: ROS and RNS production in phagocytes
Signal Transduction: Insulin receptor recycling
Gene Ontology:
Molecular function: protein binding; proton-transporting ATPase activity, rotational mechanism; ATPase-coupled ion transmembrane transporter activity
Biological process: proton transmembrane transport; regulation of macroautophagy; vacuolar acidification
Cellular component: endosome membrane; lysosomal membrane; phagocytic vesicle membrane; vacuolar proton-transporting V-type ATPase, V0 domain; membrane; proton-transporting V-type ATPase, V0 domain
Genetic constraint (gnomAD): Loss-of-function variants: 4 observed, 10.65 expected, observed/expected ratio (o/e) 0.38, 90% interval 0.18 to 0.86. The upper end of that interval is the gene's LOEUF score, 0.86, which puts it in group 3 of 6, group 1 being the genes least tolerant of losing a copy. Missense variants: 105 observed, 100.21 expected, observed/expected ratio (o/e) 1.05, 90% interval 0.89 to 1.23. Synonymous variants: 36 observed, 34.93 expected, observed/expected ratio (o/e) 1.03, 90% interval 0.79 to 1.36.
Homologues: Orthologues: rabbit ATP6V0E1 (100% identical), guinea pig ATP6V0E1 (99% identical), macaque ATP6V0E1 (99% identical), mouse Atp6v0e (99% identical), dog ATP6V0E1 (98% identical), tropical clawed frog atp6v0e1 (85% identical), zebrafish atp6v0e1 (69% identical), rat Atp6v0e1 (62% identical), Caenorhabditis elegans vha-17 (43% identical), Drosophila melanogaster VhaM9.7-b (38% identical), Drosophila melanogaster VhaM9.7-d (37% identical), Drosophila melanogaster VhaM9.7-a (36% identical), and 1 more. Paralogues in human: ATP6V0E2 (70% identical).
Diseases named in the same sentence as ATP6V0E1 in open-access papers:
ATP6V0E1 is named in the same sentence as 12 diseases in open-access papers, as found by Europe PMC text mining. Sharing a sentence is not in itself a finding about the gene and the disease. The quoted sentences say what the papers report.
esophageal cancer (1 paper, 2025). A primary or metastatic malignant neoplasm involving the esophagus. "Our in vitro and in vivo results showed that overexpression of ATP6V0E1 can dramatically promote esophageal cancer invasion and metastasis through regulation of E‐cadherin." (PMID 40729677, 2025).
insulinomas (1 paper, 2023). "In summary, these outcomes suggest that ATP4A, MCOLN1, and ATP6V0E1 are crucially ion channel-related genes in insulinoma, and the diagnostic model based on these genes was highly efficient." (PMID 37772258, 2023). "ROC curves with areas under the curve (AUC) are shown for investigating the diagnostic effectiveness of the nomogram model between insulinoma and NFPNET by using the identified three target genes (ATP4A, MCOLN1, and ATP6V0E1)." (PMID 37772258, 2023). "Since ATP4A, MCOLN1, and ATP6V0E1 might be pivotal in the ion channels for insulinoma and participate in regulating the secretion of various hormones, we selected these three target genes separately for further single-gene GSEA and GSVA analyses." (PMID 37772258, 2023). "In summary, MCOLN1, ATP6V0E1, and ATP4A might enhance the insulin secretion of insulinomas by participating in regulating the function and TGF-beta signaling pathway." (PMID 37772258, 2023).
cancer (7 papers, 2014 to 2025). A tumor composed of atypical neoplastic, often pleomorphic cells that invade other tissues. "ATP6V0E1 encodes the E subunit of the vacuolar ATPase that is important for cancer cell survival in pancreatic cancer." (PMID 38291075, 2024). "The ATP6V0E1 gene encodes a key subunit of V-ATPase, an enzyme essential for cancer cell survival." (PMID 39833504, 2025). "The V-ATPase H+ transporting genes (ATP6V0D1, ATP6V0C, ATP6V0E1) maintain the intracellular pH and thus are critical for the Warburg effect observed in the cancer cells." (PMID 38114687, 2023). "ATP6V0E1 belongs to V-ATPase family, whose members are general highly expressed in cancer cells to control the acidity of microenvironment so that metastasis and the epithelial-mesenchymal transition are promoted." (PMID 29875994, 2018). "This is confirmed by findings that cancer cells with high concentration of ATP6V0E1 or other V-ATPase family members are more resistant to anti-neoplastic drugs." (PMID 29875994, 2018). "The expression levels of TBC1D2 and ATP6V0E1 were increased in both ESCC and HNSCC tissues, and they are closely related to the overall survival of ESCC and HNSCC, which means that TBC1D2 and ATP6V0E1 could be common therapeutic targets for both cancers." (PMID 32038997, 2019). "We next investigated whether ATP6V0E1 mediates the effect of NAT10 on cancer metastasis." (PMID 40729677, 2025). "To study the biological function of ATP6V0E1 in cancer progression, we established ESCC cell lines with ATP6V0E1 overexpression or knockout." (PMID 40729677, 2025). "To further investigate whether ATP6V0E1 mediated the protein degradation in cancer cells, we performed a Western blot assay, which showed that ATP6V0E1 did not affect the total level of ubiquitin protein." (PMID 40729677, 2025).
tumor (4 papers, 2019 to 2025). "Due to the close association between the gene ATP6V0E1 and prognosis, we investigated the correlation of this gene with naive B cells, memory B cells, plasma cells, as well as its correlation with StromalScore, ImmuneScore, and tumor purity." (PMID 39744570, 2025). "Furthermore, the overexpression of ATP6V0E1 may be associated with metabolic dysregulation and immune cell suppression within the tumor immune microenvironment." (PMID 39833504, 2025). "Here, a novel role of NAT10 in inducing lysosomal acidification is revealed, and the clinical and biological significance of ATP6V0E1 in tumor metastasis is uncovered." (PMID 40729677, 2025). "They uncover the clinical and biological significance of ATP6V0E1, an important v‐ATPase assembly subunit, in tumor metastasis, particularly in the malignant progression of ESCC." (PMID 40729677, 2025). "First, we demonstrated the critical role of ATP6V0E1 in tumor metastasis, in particular, the malignant development of ESCC, for the first time." (PMID 40729677, 2025). "The levels of eight genes (SPI1, RNASE6, C1QB, C1QC, CSF1R, C1QA, TBC1D2, and ATP6V0E1) expression were higher in tumor samples from UALCAN." (PMID 32038997, 2019). "Studies suggest that ATP6V0E1 may regulate tumor cell metabolism in ESCC through oxidative phosphorylation and cuproptosis pathways." (PMID 39833504, 2025). "Moreover, ATP6V0E1 was identified as a crucial substrate for ac4C modification, and may be a prognostic biomarker and functional target for tumor metastasis." (PMID 40729677, 2025). "A series of in vitro and in vivo functional studies further confirmed that ATP6V0E1 mediates the effect of NAT10 on lysosomal degradation of E‐cadherin, cell invasion, and tumor metastasis." (PMID 40729677, 2025). "Furthermore, the clinical relevance analysis revealed that ATP6V0E1 was upregulated in ESCC tissues and further increased in metastatic tumor tissues." (PMID 40729677, 2025). "By performing immunohistochemical staining of ATP6V0E1 in a tissue microarray consisting of 211 ESCC tissues and 149 adjacent normal tissues, we noted that the expression level of ATP6V0E1 in tumor tissues was significantly higher than that in paired normal tissues (P < 0.001)." (PMID 40729677, 2025).
ATP6V0E1 also shares sentences with these, for which no sentence is quoted: diabetes (1 paper); Hepatic steatosis (1); Immune System Disease (1); infectious disease (1); metabolic syndrome (1); Obesity (1); osteoarthritis (1); pancreatic ductal adenocarcinoma (1).